MED12 (mediator complex subunit 12)
Description:
Component of the Mediator complex, a coactivator involved in the regulated transcription of nearly all RNA polymerase II-dependent genes. Mediator functions as a bridge to convey information from gene-specific regulatory proteins to the basal RNA polymerase II transcription machinery. Mediator is recruited to promoters by direct interactions with regulatory proteins and serves as a scaffold for the assembly of a functional pre-initiation complex with RNA polymerase II and the general transcription factors. This subunit may specifically regulate transcription of targets of the Wnt signaling pathway and SHH signaling pathway.
Synonyms: ARC240; Trap230; CAGH45; HOPA; KIAA0192; TNRC11; OPA1; OKS; Kto; FGS1; HDKR; MED12S; OHDOX
Tractability: PROTAC: ubiquitination databases record sites on it; its protein half-life has been measured.
Gene: Protein-coding gene on chromosome X (71,118,543 to 71,144,103, forward strand). Ensembl gene ENSG00000184634.
Subcellular location: Nucleus
Subcellular location (Human Protein Atlas): Nucleoplasm
Pathways (Reactome):
Gene expression (Transcription): Generic Transcription Pathway; MLL4 and MLL3 complexes regulate expression of PPARG target genes in adipogenesis and hepatic steatosis
Developmental Biology: Transcriptional regulation of white adipocyte differentiation
Disease: RSV-host interactions
Metabolism: PPARA activates gene expression
Gene Ontology:
Molecular function: nuclear thyroid hormone receptor binding; protein binding; transcription coactivator activity; transcription coregulator activity; nuclear vitamin D receptor binding; beta-catenin binding; chromatin binding; RNA polymerase II cis-regulatory region sequence-specific DNA binding; ubiquitin protein ligase activity
Biological process: positive regulation of DNA-templated transcription; positive regulation of transcription by RNA polymerase II; positive regulation of transcription initiation by RNA polymerase II; protein ubiquitination; regulation of transcription by RNA polymerase II
Cellular component: CKM complex; mediator complex; membrane; nucleus; nucleoplasm; ubiquitin ligase complex
Gene-disease validity (ClinGen):
ClinGen rates the evidence that MED12 causes each of these diseases.
MED12-related intellectual disability syndrome (X-linked): Definitive. An X-linked syndromic intellectual disability that that includes subtypes of the heterogeneous, eponymously named Lujan-Fryns syndrome, X-linked Ohdo syndrome, and Optiz-Kaveggia/ FG syndrome, which is caused by mutations in the gene MED12.
Cancer hallmarks: proliferative signalling (promotes); invasion and metastasis (suppresses); genome instability and mutations (promotes)
Homologues: Orthologues: macaque MED12 (99% identical), pig MED12 (98% identical), chimpanzee MED12 (98% identical), mouse Med12 (97% identical), rat Med12 (97% identical), rabbit MED12 (94% identical), tropical clawed frog med12 (77% identical), guinea pig MED12 (77% identical), zebrafish med12 (73% identical), Drosophila melanogaster kto (40% identical), Caenorhabditis elegans dpy-22 (26% identical). Paralogues in human: MED12L (61% identical).
Diseases named in the same sentence as MED12 in open-access papers:
MED12 is named in the same sentence as 136 diseases in open-access papers, as found by Europe PMC text mining. Sharing a sentence is not in itself a finding about the gene and the disease. The quoted sentences say what the papers report.
leiomyoma (85 papers, 2011 to 2026). A well-circumscribed benign smooth muscle neoplasm characterized by the presence of spindle cells with cigar-shaped nuclei, interlacing fascicles, and a whorled pattern. "MED12 wild-type leiomyomas have a higher growth potential than mutant leiomyomas, suggesting that the mutation limits leiomyoma growth." (PMID 41493967, 2026). "While MED12 mutations can be found in up to 70–80% of leiomyomas, they are less frequent (2–30%) in leiomyosarcomas." (PMID 41162745, 2025). "The role of a different mediator subunit, MED12, has been previously implicated in the pathogenesis of leiomyoma, with a recent meta-analysis finding MED12 mutations in 55.8% of leiomyomas analyzed." (PMID 40290045, 2025). "The third theory suggests genetic tendencies toward leiomyoma development implicated through molecular alterations in MED12 and HMGA2 genes." (PMID 40115706, 2025). "Collectively, these findings reinforce the concept that MED12 mutations reshape the transcriptional landscape of leiomyomas and provide mechanistic clues to their initiation and growth." (PMID 41156009, 2025). "Leiomyoma development from cells with mutated MED12 is thought to occur through increased AKT signaling and decreased cyclin C-CDK8/19 kinase activity, leading to myometrial cell growth and proliferation." (PMID 40290045, 2025). "For example, targeted expression of a mutant MED12 allele (c.131G>A; p.G44D) in the uterine mesenchyme of mice was sufficient to induce leiomyoma formation, providing direct genetic proof of causality." (PMID 41156009, 2025). "Three well-established driver alterations in leiomyomas are MED12 mutations, chromosomal rearrangements leading to HMGA2 overexpression, and biallelic mutations resulting in FH-deficiency, which together account for 80–90% of the tumors." (PMID 41162745, 2025). "Leiomyoma-associated driver alterations in MED12, HMGA2, and FH have been reported in up to one-third of uterine leiomyosarcomas." (PMID 41162745, 2025). "Epigenetics and transcriptional changes play an important role in the development of leiomyomas, as shown by the frequent mutations in MED12, a subunit of the Mediator complex." (PMID 40345582, 2025). "Within patients, individual fibroids are thought to independently occur as evidenced by unique mutation burdens, with some patients harboring up to 5 different MED12 mutations across 5 different fibroids." (PMID 38957794, 2024). "In summary, our data provide a comprehensive expression profile of lncRNAs in leiomyomas and demonstrate the influence of race/ethnicity and MED12 mutation on their expression, indicating their relevance to fibroid pathogenesis." (PMID 38279317, 2024). "One recent study suggested the leading role of HMGA2 aberrations in uterine leiomyoma tumorigenesis, which is overexpressed even in leiomyomas with MED12 mutation." (PMID 37466765, 2024). "The MED12 gene, located on chromosome Xq13.1, expresses missense gain of function mutations in leiomyomas which typically occur in exon 2 or rarely in the intron-2-exon-2 junction." (PMID 38957794, 2024). "More recently, a role for MED12 in tumor initiation has been proposed, as evidenced by the development of leiomyoma-like tumors in transgenic mice with a uterine conditional mutation in MED12." (PMID 38279317, 2024). "MED12 mutations, which occur in up to 80% of leiomyomas, are associated with abnormal activation of Wnt/β-Catenin signaling, sex steroid receptor signaling, and increased expression of genes related to cell proliferation and fibrosis." (PMID 39519092, 2024). "Whole genome sequencing has elucidated the genetic foundation of ULM, revealing that over 70% of leiomyoma (LM) cases harbor mutations in the mediator complex subunit 12 (MED12), with mutation rates positively correlating with tumor quantity." (PMID 39640883, 2024).
leiomyoma (continued). "Fibroids are frequently associated with genetic alterations affecting mediator complex subunit 12 (MED12), fumarate hydratase (FH), high mobility group AT-hook 2 (HMGA2) and collagen, type IV alpha 5 and alpha 6 (COL4A5-COL4A6)." (PMID 37113812, 2023). "In leiomyoma, somatic MED12 mutations in exon 2 occur at a frequency of up to 80% regardless of race/ethnicity." (PMID 36835153, 2023). "Although we did not detect mutations in the MED12 gene in any myometrial tissues, we observed marked differences in the expression profile in the myometrium adjacent to MED12-mutated leiomyomas compared with the myometrium adjacent to MED12 wild-type tumors." (PMID 36835153, 2023). "Of the driver mutations, MED12 gene mutations have gained the most attention in the pathophysiology of leiomyomas." (PMID 36835153, 2023). "Mutations in MED12 exon 2 were found in 70% of fibroids, and MED12m-related fibroids were smaller in size but more numerous compared to the wild type." (PMID 37107181, 2023). "A hotspot mutation in MED12 or a chromosomal rearrangement of HMGA2 that leads to a significant HMGA2 overexpression account for 80%–90% of all leiomyomas." (PMID 35822448, 2023). "Recent studies have demonstrated that somatic MED12 mutations in exon 2 occur at a frequency of up to 80% and have a functional role in leiomyoma pathogenesis." (PMID 36835153, 2023). "Mutations in exon 2 of MED12 are gain-of-function mutations, as evidenced by transgenic mice which developed leiomyoma-like tumors in the uterus when a conditional mutation in MED12 was introduced." (PMID 36835153, 2023). "HMGA2 rearrangements have been associated with larger tumor size and a smaller number of tumors compared with leiomyomas with a MED12 mutation." (PMID 35822448, 2023). "What is already known on this subject: The majority of fibroids harbor mutations as high as 60% in relation to the most common genetic driver in uterine fibroid that is MED12." (PMID 37113812, 2023). "High rate of MED12 mutations and leiomyoma burden are clearly associated with myometrial oxidative stress." (PMID 35869560, 2022). "Makinen’s group has identified recurrent somatic mutations in MED12 that drive leiomyoma development." (PMID 35203298, 2022). "Chromosomal and/or genetic alterations are known causes of leiomyoma formation, and the mutations affecting mediator complex subunit 12 (MED12) were found only in fibroid stem cells." (PMID 35585291, 2022). "Kurita’s group has recently reported that subtypes of leiomyoma with either MED12 mutations or HMGA2 overexpression required progesterone and 17β-estradiol to stimulate tumor growth." (PMID 35203298, 2022). "Several studies point to specific genetic mutations that lead to the development of fibroids, specifically the “MED12, HMGA2, COL4A5/COL4A6, FAS or FH genes”." (PMID 36703761, 2022). "More recently, Corachán and collaborators evaluated the effects of vitamin D on the Wnt/β-catenin and TGFβ signaling pathways in human uterine leiomyoma primary (HULP) cells isolated from mediator complex subunit 12 (MED12) -mutated and wild type leiomyomas." (PMID 33670322, 2021). "Expression of Wnt/β-catenin and TGF β pathway genes is, in fact, significantly increased in MED12-mutated leiomyomas." (PMID 33670322, 2021). "Genome wide exome sequencing showed that between 50–70% of fibroids, depending on patient ethnicity and fibroid number, contained mutations primarily in the second exon of the Mediator Complex subunit 12 (MED12) gene." (PMID 33807176, 2021). "Concerning other less frequent mutations, it is important to observe that MED12 mutations are rare (11%), with striking difference with respect to benign leiomyomas, which are reported to carry MED12 exon 2 mutations in roughly 70% of cases." (PMID 32751892, 2020).
leiomyoma (continued). "Principal component analysis using the 3′RNA sequencing data revealed that the 49 (44 leiomyomas + 5 myometrium) samples and 11 technical replicates grouped according to the predetermined mutation status of MED12, HMGA2, and FH." (PMID 33352722, 2020). "Consistent with published data, samples of co-occurring endometriosis in some of our adenomyosis patients bore both KRAS and PIK3CA mutations, whereas most co-occurring leiomyoma samples harbored MED12 mutations." (PMID 31857578, 2019). "Mutations of MED12 and/or FH, which are common in leiomyoma and show high VAFs, have been reported in ~10% of adenomyosis and adenomyotic polyps." (PMID 31857578, 2019). "Increased expression of WNT4 has been found in studies of fibroid tumors that carry somatic MED12 mutations." (PMID 31249589, 2019). "Most genetically mutated tumors (27/30; 90%) demonstrated only one type of genetic change, highlighting that even single allele change in MED12 can have profound impact in transforming the normal uterine myometrium to leiomyomas." (PMID 30619444, 2018). "We discovered that >44% (34/77) leiomyomas of Arab women carry a spectrum of MED12 mutations (30 missense, 1 splice site, and 3 indels)." (PMID 30619444, 2018). "MED12 mutated leiomyomas (with ≥5.5 cm in diameter) collected from South African women revealed the high number of mutations in large tumors compared to smaller ones." (PMID 30619444, 2018). "The ascertainment of MED12 causal role in leiomyoma genesis can be done through functional biology assays or through gene knockout in animal models." (PMID 30619444, 2018). "We compared the biochemical characteristics like prolactin, luteinizing hormone (LH), estradiol, progesterone, and total cholesterol in leiomyoma patients to examine the influence of MED12 mutations on clinical and biochemical characteristics." (PMID 30619444, 2018). "This suggests us that even single allele change in MED12 gene can have profound impact in transforming the normal uterine myometrium to leiomyomas." (PMID 30619444, 2018). "Patients with MED12 mutation in leiomyoma have larger tumors (7.99 ± 3.9 cm; p = 0.02), high BMI (33.84 ± 6.9 kg/m2; p = 0.04) and low serum levels of luteinizing hormone (13.8 ± 8.4 mU/L; p = 0.02) compared to women who are not carrying the mutation." (PMID 30619444, 2018). "Owing to the lack of studies, present study has aimed to establish the role of somatic mutation in MED12 gene in leiomyomas of Saudi patients." (PMID 30619444, 2018). "In compliance to the previous findings about MED12 genetic alterations in leiomyomas of different ethnic groups, our study affirms that MED12 mutation positivity is critical to development and progression of ULs irrespective of ethnic background." (PMID 30619444, 2018). "Regarding the association analysis, a significant positive correlation in groups (+ve and −ve for MED12 mutations) between leiomyoma size with BMI, and prolactin (p for all tests is < 0.05) were observed." (PMID 30619444, 2018). "In a recent study, MED12 mutations were also found in 10 out of 29 (34%) cases of leiomyoma/leiomyomatosis in pelvic/retroperitoneal sites." (PMID 28591699, 2017). "This study confirmed the association of MED12 mutations with smaller leiomyoma size, multiplicity and conventional histotype, and revealed novel associations between the MED12-mutation status and leiomyoma location, PID, and parity." (PMID 28432313, 2017). "MED12 mutations were the most common alterations in conventional and mitotically active leiomyomas and leiomyosarcomas, while leiomyomas with bizarre nuclei were most often FH deficient and cellular tumors showed frequent HMGA2 overexpression." (PMID 28592321, 2017). "Subsequent studies have indicated that histopathological UL subtypes harbor significantly fewer MED12 mutations than conventional leiomyomas." (PMID 28592321, 2017).
leiomyoma (continued). "As previously reported, the histopathological UL variants (18.1%, 17/94) harbored significantly fewer MED12 mutations than the conventional leiomyomas (56.9%, 37/65; P = 5.2 × 10−7)." (PMID 28592321, 2017). "The median number of leiomyomas was 2 (range 1–16), the median number of MED12-mutation-positive tumours was 2 (range 0–16), and the median number of mutation-negative tumours was 1 (range 0–5) per patient." (PMID 28432313, 2017). "In this prospectively collected leiomyoma series, the frequency of MED12 mutations reached 79%, being among the highest ones reported." (PMID 28432313, 2017). "The most prevalent alterations in conventional ULs were only rarely observed in leiomyomas with bizarre nuclei: MED12 mutations were identified in three out of 18 tumors (16.7%) and none displayed HMGA2 overexpression." (PMID 28592321, 2017). "Second, we examined the associations between clinical factors and the number of MED12-mutation-positive leiomyomas." (PMID 28432313, 2017). "The inverse association between the number of MED12-mutation-positive leiomyomas and parity suggests that births reduce the risk specifically for this leiomyoma subgroup." (PMID 28432313, 2017). "This is, to our knowledge, the first study to show that positive MED12-mutation status is associated with subserosal location of leiomyomas." (PMID 28432313, 2017). "This study examined the associations between MED12-mutation status, tumour characteristics, and various clinical factors in a large sample set of leiomyomas." (PMID 28432313, 2017). "In 2014, mutations in exon 2 of the MED12 gene were reported in 34% of leiomyomas/leiomyomatoses of pelvic/retroperitoneal sites." (PMID 28591699, 2017). "New fundamental insights into the etiology of fibroids will arise from the latest development in research regarding the MED12 mutation which is a driver mutation for fibroids with very high prevalence rate." (PMID 27138351, 2016). "Fourteen (78%) of the 18 leiomyoma specimens had somatic mutations (a single nucleotide mutation in 13 specimens and a deletion mutation in 1 specimen) in MED12." (PMID 27498619, 2016). "Recently, however, mutations in exon 2 of the mediator complex subunit 12 (MED12) gene were found in 10 out of 29 (34%) leiomyomas/leiomyomatoses in pelvic/retroperitoneal sites." (PMID 25621995, 2015). "In a recent study, MED12 mutations were also found in 34% of leiomyoma/leiomyomatosis in pelvic/retroperitoneal sites but there was no information about the status of HMGA2 and HMGA1." (PMID 25621995, 2015). "Recently, MED12 mutation was reported in a high percentage of leiomyoma and has direct interactions with beta catenin, as does MED19." (PMID 23785396, 2013). "Quite recently, mutations of mediator subcomplex 12 (MED12), have been described in a majority of fibroids." (PMID 23738817, 2013). "We isolated RNA and generated cDNA from a random selection of ten leiomyomas known to carry MED12 DNA variants." (PMID 22428002, 2012). "Our study on outbred American women, including both white and black individuals, further extends the association of MED12 variants and leiomyomas in various ethnic and racial groups." (PMID 22428002, 2012). "Recently, mutations in the MED12 gene have been reported in the majority of leiomyoma tissues and cells." (PMID 22570742, 2012). "Fifty-nine of 85 leiomyomas (69%) with a normal karyotype harbored MED12 variants, while 31/49 leiomyomas (63%) with an abnormal karyotype had MED12 variants." (PMID 22428002, 2012). "Our studies show an association between MED12 mutations and leiomyomas in ethnically and racially diverse American women." (PMID 22428002, 2012). "Sanger re-sequencing of MED12 among these five leiomyomas confirmed the two single nucleotide variants and detected a 42 base-pair deletion within exon 2 of MED12 in a third leiomyoma." (PMID 22428002, 2012).